IL6 (interleukin 6)
Diseases named in the same sentence as IL6 in open-access papers (continued):
Sharing a sentence is not in itself a finding about the gene and the disease.
cancer (continued). "Likely candidates for this activation are IL-6 and G-CSF as neutralisation of IL6/G-CSF/MEK1/2 mitigated phosphorylation of ERK concomitant with reductions in cancer cell proliferation and invasion." (PMID 37703292, 2023). "Of the increased pro-inflammatory cytokines, IL-6 and IL-8 level greatly elevated in cancer cell treated with SP, as compared with other cytokines." (PMID 36685035, 2023). "In this research, we found that the anti-inflammatory and anti-cancer marine natural compound SC-1 blocks TGFβ-induced IL-6 expression." (PMID 37511415, 2023). "Ectopic addition of IL-6 rescued cancer cell migration, proliferation, and invasion when Stattic was used as a monotherapy; however, combination with tocilizumab maintained inhibitory activity, even under high dose IL-6 stimulation." (PMID 37173951, 2023). "In contrast, p38α has also been shown to support cell survival via anti-apoptotic inflammatory signals interleukin-6 (IL-6) and enable DNA-repair after chemotherapy which results in drug-resistance in cancer cells." (PMID 37248432, 2023). "Other SASP factors that facilitate EMT in cancer cells include the pro-inflammatory factors IL-6 and IL-8, Serine protease inhibitor Kazal-type 1 (SPINK1), amphiregulin (AREG), epiregulin (ERPG), and WNT16B." (PMID 37046588, 2023). "IL-6 is highly expressed in some cancers, including breast cancer, lung cancer, stomach cancer, liver cancer and ovarian cancer." (PMID 36845384, 2023). "Interleukin-6 (IL-6) has been shown to have a direct stimulatory effect on many cancer cells through its action on several cell cycle pathways." (PMID 37047012, 2023). "Research in mouse models of cancer cachexia found that the anti-inflammatory cytokines TNFα and IL-6 were significantly inhibited, and the biochemical parameters were enhanced after the administration of oral L-carnitine." (PMID 36975525, 2023). "IL-6 is one of the pro-inflammatory cytokines released either by cancer cells and or by stromal cells." (PMID 36675246, 2023). "Anti-IL-6 monoclonal antibodies such as sirukumab, olokizumab, MEDI5117, and clazakizumab have been used as inhibitors of the IL-6/JAK/STAT3 signaling pathway in various cancers." (PMID 37174117, 2023). "Cancer cells express various cytokines, chemokines, and growth factors such as IL-6, CCL2, CXCL8, CSF1, and CSF2, which impact vascular permeability, lymph angiogenesis, and metastasis." (PMID 37894465, 2023). "Plasma concentrations of the inflammatory biomarkers CRP, IL‐6 and YKL‐40 are associated with poor prognosis in patients with advanced cancer." (PMID 36440611, 2023). "We found that neutralizing antibodies against IL-6 and G-CSF starting 2 days prior to docetaxel treatment significantly inhibited chemotherapy-induced cancer cell proliferation, as shown by fewer yellow-green cells." (PMID 37699010, 2023). "IL-6 was released by several cell populations in malignant effusion, including cancer cells, macrophages, mesothelial cells 17-20." (PMID 37215450, 2023). "This research confirmed the potential therapeutic use of IL-6 inhibitors to improve anti-cancer drug sensitivity in gastric malignancy cells." (PMID 37062547, 2023). "The study therefore revealed that luteolin can affect the IL-6 signaling pathway and in the end reduce the cancer cell proliferation and metastases." (PMID 37958980, 2023). "A synthetic analog of chrysin named 8-bromo-7-methoxy chrysin inhibits the activation of hepatic stellate cells to CAFs, thereby reducing the stemness of cancer cells by impeding IL-6 and HGF signaling." (PMID 37065872, 2023). "IL-6 signaling plays a crucial role in inflammation and cancer development, and several monoclonal antibodies targeting IL-6 or IL-6R have been developed as therapeutic agents for inflammatory diseases and cancers." (PMID 37759507, 2023).
cancer (continued). "This is further recapitulated in ingenuity pathway analysis (IPA), as enriched terms to psPD represent several immune response pathways driven by TREM1, TNF, IFNG, IL1, and IL6 while PD was primarily demarcated by E2F-mediated cancer activity." (PMID 38049893, 2023). "Given that IL-6 plays a more significant role in inflammatory diseases than in cancer development, we intend to explore the therapeutic potential of SC-1 in the treatment of various inflammatory conditions." (PMID 37511415, 2023). "IL-6/gp130/STAT3 signaling is involved in cancer progression and drug resistance in various human cancers, including ovarian, breast, gastric, and colon." (PMID 36495330, 2023). "This phenotype was reversed by the addition of piRNA 823 antagomir or DNMT3B inhibitor, demonstrating that IL-6 can also enhance the stemness in cancer cells, hence treatment resistance of MM by inducing epigenetic changes." (PMID 37808081, 2023). "The relationship between chronic inflammation, as measured by inflammatory circulating biomarkers including C‐reactive protein (CRP) and interleukin‐6 (IL‐6), and cancer incidence has recently been described in a systematic review and meta‐analysis." (PMID 36440611, 2023). "Accordingly, this SHP2-PDHA1-ROS regulatory axis was crucial for adipocyte maintenance and secretion of interleukin-6 (IL-6), a key cancer-promoting cytokine." (PMID 36074246, 2023). "iCAFs localised distantly from cancer cells and were characterised by lower expression of αSMA and high level of inflammatory mediators such as interleukin-6 (IL-6), IL-11, and leukaemia inhibitory factor (LIF)." (PMID 35767180, 2023). "The IL‐6/JAK/STAT3 signaling pathway is frequently overactivated in various cancer types, and its dysregulation is commonly correlated with unfavorable clinical outcomes." (PMID 38125769, 2023). "Increases in adipose tissue volume and macrophage influx result in higher levels of fever-inducing proinflammatory cytokines (TNF-α, IL-1β, and IL-6), already increased as a consequence of cancer." (PMID 37374212, 2023). "Inflammation-based therapies primarily target inflammatory cytokines such as interleukin-6 (IL-6) in T cells, macrophages, cancer cells, and muscle cells, and there is a limited understanding of how these cytokines act on endothelial cells." (PMID 37735165, 2023). "TNF-α, similarly to IL-6, is a proinflammatory cytokine characterized by a broad spectrum of functions which also include cytotoxic and cytostatic effects against cancer cells and in MCF-7 cells." (PMID 36903346, 2023). "Genotoxic stress in STING-positive cancers causes activation of this pathway, and some cells activate the non-canonical STING pathway, leading to abundant secretion of immunosuppressive IL-6 (this pathway also requires inhibition of ERK1/2." (PMID 38139802, 2023). "In the rat glia cell line C6, LRRC15 is mildly regulated in response to proinflammatory cytokines like IL1β, IL6, and TNFɑ, and more recently TGFβ signaling has been linked to LRRC15 expression in cancer-associated fibroblasts." (PMID 36757924, 2023). "In this review, we show that phosphoflow cytometry has been applied to study a number of important cytokine signaling pathways in peripheral blood of cancer patients, including signaling induced by interferon, IL-6, and IL-7." (PMID 37741983, 2023). "According to previous research, there is a parallel increase in VEGF and IL-6 levels observed in patients with cancer, similar to the results seen in our study." (PMID 36873124, 2023). "Among those, IL6 has both pro- and anti-inflammatory properties, and pro-inflammatory signals are predominant in the pathogenesis of cancer." (PMID 36900301, 2023). "Epithelial-mesenchymal transition (EMT) is a vital step in the early stages of cancer metastasis and orchestrated by multiple signaling pathways, such as IL-6/JAK/STAT3 and TGF-β/Smad signaling pathway." (PMID 37742009, 2023).
cancer (continued). "Knockdown of GLUT5 has been reported to eliminatefructose uptake and utilization by oral squamous cell carcinoma and prostate cancer cellsinduced by interleukin-6 and inhibit cancer cell proliferation." (PMID 37674366, 2023). "In certain models of TNBC cells exhibiting high CIN, a reduction in cGAS–STING levels resulted in decreased IL-6 production and reduced survival of cancer cells." (PMID 38139802, 2023). "(−40%) of male CHXIL6KO mice compared with male CHXscr mice, suggesting that cancer cell‐derived IL‐6 initiates cachexia in CHX207 mice." (PMID 36351437, 2023). "We found that in the co-culture of endotoxin-tolerant macrophages and cancer cells, the lower level of both IL-6 and TNFα cytokines was still observed." (PMID 37894480, 2023). "Studies have indicated that IL-6 promotes the proliferation, metastasis, and chemoresistance of cancer cells, and induces the secretion of pro-inflammatory factors that contribute to an immunosuppressive TME." (PMID 36635302, 2023). "As chronic inflammation is a key risk factor for developing various malignancies, inflammatory mediators, including IL-6 and TNFα are known to be involved in carcinogenesis and cancer progression." (PMID 37628724, 2023). "CAFs strongly induce IL-6-mediated cell motility in conditioned medium, but pretreatment with resveratrol completely prevented cancer cell motility, simultaneously reversing the N-to-E cadherin switch." (PMID 37560476, 2023). "IL-6 and oncostatin M have been found to directly stimulate enhanced invasion of cancer cells, stimulate the promotion of cell cycle, enhance resistance to chemotherapy, and cause epithelial-to-mesenchymal transition (EMT)." (PMID 37322531, 2023). "First, we tested the cytokine production (IL-1β, IL-6, and IFNα) of peripheral blood mononuclear cells (PBMCs) co-incubated with cancer cells by FACS analysis." (PMID 36831616, 2023). "The biological behavior of cancer cells to generate EMT will be regulated by a large number of growth factors and cytokines including TGF-β, IL-6, EGF, VEGF and HGF, secreted from Cancer-associated fibroblasts (CAFs)." (PMID 37880742, 2023). "Blocking IL-6 has been shown to be beneficial in cancer patients when combined with other conventional therapies." (PMID 38127882, 2023). "Particularly, factors related to epithelial-mesenchymal transition, TNFA, and IL6/JAK/STAT signaling were elevated in basal cancer cells along with signatures for inflammatory response and IFNG response." (PMID 37633924, 2023). "For example, IL-6 inhibition by neutralizing antibody was found to reduce the metastatic potential of gastric, bladder, and lung cancer cells." (PMID 37941042, 2023). "CAFs, the most abundant cells in TME, secrete substances such as transforming growth factor-β (TGF-β), vascular endothelial growth factor (VEGF), and interleukin-6 (IL-6) which can promote cancer progression." (PMID 37480115, 2023). "In this study, we identified high IL-6 levels as a feature of atezolizumab (anti-PD-L1)-resistant disease in patients with advanced cancers." (PMID 36599350, 2023). "Because of this, the effects IL-6 has on cancer cells of CAC and other forms of colorectal cancer are likely mediated by STAT3." (PMID 38002302, 2023). "In ccRCC, cancer-cell-derived factors such as IL-1β, IL-6, IL-10, tumor necrosis factor-α, epidermal growth factor, and TGF-β induce macrophage polarization towards a M2 phenotype by cell-cell interactions." (PMID 37842234, 2023). "Blocking IL-6 in cancer patients was previously reported to be beneficial when combined with other conventional therapies." (PMID 36673615, 2023). "A pleiotropic inflammatory cytokine IL-6 is considered a key factor in the growth of malignant neoplasms and metastases." (PMID 36982207, 2023). "Positive correlations of VEGF-A among CCL2, IL-6, and IFN-γ and between IFN-γ and IL-6 were observed in Cancer TIF1-γ-DM patients." (PMID 36357631, 2023).
cancer (continued). "Cut-off values for Il-6 for malignant tumors were 11.3 pg/mL and 7.2 pg/mL for the control group, while in our study, the values were 16.76 pg/mL and 5.9 pg/mL." (PMID 37373969, 2023). "Elevated sTNFR1 levels in cancer patients after administration of recombinant IL-6 have been also observed." (PMID 36928833, 2023). "PIGF signaling activates inflammatory cytokine releasing, such as IL-1β and IL-6, to promote angiogenesis in several types of cancer." (PMID 35895109, 2023). "Increasing with cancer progression, the concentration of MGAs positively correlated with the secretion of ILs: IL-1β, IL-2, IL-4 and IL-6." (PMID 37970208, 2023). "For example, abnormal activation of IL-6-mediated JAK/STAT3 signal transduction frequently occurs in human cancers and is involved in transformation, tumorigenicity, EMT, and metastasis." (PMID 36911202, 2023). "Interleukin 6 (IL-6) is a pleiotropic secreted cytokine produced by many cell types, including immune, stromal, and cancer cells, and regulates cellular responses to stressors." (PMID 37385076, 2023). "As with other senescent markers, we found that the Ca + aMCI group had IL-6 and IL-8 mRNA levels comparable to healthy controls and cancer survivors and lower than the aMCI group." (PMID 37108527, 2023). "IL6 is involved in the pathogenesis of several cancer types and autoimmune diseases and thus has already become a therapeutic target in some of these conditions, such as rheumatoid arthritis." (PMID 37958474, 2023). "We also observed a trend toward higher serum concentrations of IL-6, a cancer-promoting cytokine, in some vehicle-treated mice (379.1pg/ml) compared to MRX2843-treated mice (45.4pg/ml, p=0.3)." (PMID 36960055, 2023). "This, in turn, promoted MSC survival and IL-6 and IL-8 secretion, which affected cancer cells’ chemoresistance." (PMID 37175439, 2023). "Bifidobacterium can exert a preventive effect against cancer by lowering IL-6 levels through regulating gut microbiota and immune system mechanisms." (PMID 37381018, 2023). "In the endothelin pathway, the expression of interleukin-6 (IL-6) and interleukin-8 (IL-8) molecules in cancer cells increases when gap junctions are established." (PMID 37056723, 2023). "One such anti-IL-6 treatment, celecoxib, evaluated in clinical trials for cancer cachexia, produced remarkable improvements in lean body mass and grip strength." (PMID 37755304, 2023). "Since it is necessary to understand how Fc-VFD targets cancer cells, we showed that the IL-6 and VEGF-A expression in both SW620 and HT29 cells follows a dose-dependent manner." (PMID 35895109, 2023). "For the part of inflammation in cancer, the following keywords were used: cytokines in cancer, inflammation in cancer, IL-6 in cancer, IL-10 in cancer, and TNF-α in cancer." (PMID 36771154, 2023). "Prolonged activation of IL-6 signaling induces excessive consumption of adipose tissue and increases energy expenditure in cancer by accelerating lipolysis and adipose tissue browning." (PMID 36670439, 2023). "Collectively, our study urges caution when using svLAAOs in cancer treatment and identifies the Panx1/iCa2+/IL-6 axis as a therapeutic target for improving the effectiveness of svLAAOs-based anticancer therapies." (PMID 37385076, 2023). "It stimulates cancer growth and prevents apoptosis, suggesting that IL-6 is a potential treatment target." (PMID 36831406, 2023). "CHX207 mice share important features of CAC with other allograft cancer models such as C26, including the IL‐6 dependence of CAC pathogenesis and many aspects of lipid and muscle metabolism." (PMID 36351437, 2023). "The occurrence of cancer-related muscle loss is profoundly influenced by cytokine-mediated inflammation, specifically involving TNF-α, interleukin-1 (IL-1), IL-6, and interferon-gamma (IFNγ)." (PMID 37959329, 2023). "These adipocytes secrete a number of proinflammatory cytokines, such as IL-1, IL-6, and IL-8, which induce inflammation and various cancers." (PMID 37760423, 2023).
cancer (continued). "CAAs increase the release of IL-6 to expand the cancer stem cell population by activating an IL-6 inflammatory loop, which results in anti-trastuzumab effects in HER2+ BC patients that is overcome by an IL-6 receptor antibody." (PMID 36765683, 2023). "In this review, inflammatory processes in cancer are discussed, focusing on cytokines IL-6, IL-10, and TNF-α, which play an important role in the inflammatory response, preventing or increasing different disorders, including cancer." (PMID 36771154, 2023). "Studies have shown that IL-1β, TNF-α, and IL-6 are the most substantially changed cytokines in cancer, and their levels can even be related to cancer stage." (PMID 36627634, 2023). "The opposite effect of P4 on cytokine production in cancerous and noncancerous cells has been demonstrated in studies: P4 mostly down-regulated IL-1β, IL-6, and TNFα in cancer cell lines and tissues." (PMID 37298830, 2023). "The cancer cells containing DNA double-strand breaks increased IL-6 secretion by DNA damage response proteins such as ataxia-telangiectasia-mutated during oncogene-induced senescence." (PMID 37480115, 2023). "It is also intriguing to note that recent evidence has revealed a role for CAF-produced IL-6 in a number of cancers where its expression is correlated with poor prognosis." (PMID 37660739, 2023). "IL6 is a proinflammatory cytokine released by various cells and plays a critical role in expansion and differentiation of cancer cells." (PMID 37238004, 2023). "In accordance with earlier studies of patients with cancer, we found that high plasma concentrations of CRP, IL‐6 and YKL‐40 either alone or combined were associated with short OS in patients suspected of cancer." (PMID 36440611, 2023). "STING also activates NF-κB, which promotes progression and resistance to therapy by inducing the production of inflammatory cytokines, including IL-6, which is required for the survival of cancer cells following genotoxic treatments." (PMID 37036972, 2023). "For example, one study found increased serum levels of IL-6 and IL-7 (cancer-suppressive) in CD, and increased TNF-α, eotaxin and growth-related oncogene (a chemokine) in UC patients." (PMID 37681925, 2023). "Functions of certain cytokines are explored; CCA and cancer stromal cells secrete inflammatory cytokines, such as IL-1, IL-6, IL-8, IL-10, TNF-α, and TGF-β, to promote cancer growth, metastasis, and immune evasion." (PMID 36883059, 2023). "Exercise intervention studies have reported results on the reduction of inflammatory biomarkers associated with cancer including C-reactive protein (CRP), interleukin-6 (IL-6) and tumor necrosis factor-α (TNF-α)." (PMID 35779184, 2023). "Nevertheless, among factors attributed to cancer transformation, pro-inflammatory cytokines are seen, including IL-6 and IL-8." (PMID 37047238, 2023). "Serum levels of IL-6, TNF-α, and other inflammatory and cancer-associated cytokines, as well as WBC, NEU, and CRP values, have a certain correlation with the development and progression of GLM; thus, they can reflect the disease to a certain extent." (PMID 37817809, 2023). "Inflammation has arisen as a viable cause both in CV disease and cancer, because correlation between tumour biomarkers and proinflammatory cytokines, such as TNF-α, IL-6 and IL-10, has been identified." (PMID 36830690, 2023). "By regulating the expression of target genes (including VEGF and IL-6) and stimulating neoangiogenesis, NF-κB also promotes cancer cell proliferation and survival." (PMID 37211559, 2023). "While these anti-inflammatory agents targeting TNF-α and IL-6 have shown some positive results, further research is needed to fully understand their clinical efficacy in treating cancer cachexia." (PMID 37755304, 2023). "Pro-inflammatory cytokine Interleukin-6 (IL-6) is considered a central mediator of cancer cachexia, with IL-6 levels correlating positively with the progression of cachexia." (PMID 38046952, 2023).